UCP1 (uncoupling protein 1)
Diseases named in the same sentence as UCP1 in open-access papers (continued):
Sharing a sentence is not in itself a finding about the gene and the disease.
Obesity (continued). "In a diet-induced obesity model, the PPARα agonist fenofibrate, elicits weight loss and increases β3-AR, PGC-1α and UCP-1 in brown adipocytes." (PMID 31346342, 2019). "We also analyzed the mRNA expression of β3AdR in adipocytes, and the same trends as for UCP1 and NE were observed: obesity increased β3AdR expression, and infection with H. polygyrus had additional effects." (PMID 30962398, 2019). "The ability of CAP to enhance SiRT-1 activity to promote the browning phenomenon in WAT and UCP-1-mediated thermogenesis are important for the anti-obesity effect of CAP." (PMID 31197191, 2019). "Brown adipose tissue plays a major role in regulating whole body glucose and lipid homeostasis under cold conditions (i.e., when UCP1 is active) with apparent anti-obesity potential in rodents." (PMID 31086124, 2019). "UCP1 activation, therefore, represents a potential protective mechanism against obesity, diabetes, and dyslipidemia." (PMID 31817377, 2019). "In line with the ability of casein intake to attenuate obesity development, the classic brown adipose tissue morphology and high UCP1 expression in iBAT were maintained after feeding lean mice a casein-based HF/HP diet." (PMID 31126082, 2019). "In thisphenomenon participate the uncoupling proteins (UCPs) and in consequence, the genesthat encode these molecules (UCP1, UCP2 andUCP3) are regarded as candidate genes for obesity, T2DM andcardiovascular disease." (PMID 29786102, 2018). "As opposed, EPA has been demonstrated to prevent obesity increasing thermogenesis through uncoupling protein 1 (UCP-1), which represents a biomarker for brown adipose tissue (BAT)." (PMID 30217048, 2018). "The UCP1 and NPC1 genes are known to be involved in the regulation of energy metabolism and the role of the polymorphisms in these genes with respect to obesity is arguable due to the diverse results of studies performed in different ethnicities." (PMID 30458724, 2018). "Our findings are in agreement with this, as scWAT ITGA4 mRNA expression decreased and UCP1 expression increased in the entire sample and in all BMI groups, particularly in the obesity group." (PMID 30618796, 2018). "Conversely, deletion of UCP1 induces obesity by abolishing diet-induced thermogenesis in mice kept at thermoneutral temperature, regardless of the type of diet (normal chow, high-fat)." (PMID 30275865, 2018). "Recent studies already suggested for WAT the involvement of a futile substrate cycle based on TAG lipolysis and energy demanding re-esterification as an UCP1 independent anti-obesity effect of n-3 LCPUFA." (PMID 30275870, 2018). "Browning of adipose tissue has been prescribed as a potential way to treat obesity, marked by the upregulation of uncoupling protein 1 (Ucp1)." (PMID 30126161, 2018). "Accordingly, we observed the lowest baseline UCP1 expression levels in individuals with obesity, while the exercise intervention increased UCP1 expression to levels comparable to those of Nw group." (PMID 30618796, 2018). "Expression of adipocyte-specific UCP1 leads to prevention of obesity by modulating mitochondrial membrane potential." (PMID 30275865, 2018). "Their work suggested that the UCP1-independent energy dissipation linked to futile triacylglycerol/fatty acid cycling may contribute to non-shivering thermogenesis as well as the observed amelioration of obesity induced by calorie restriction combined with the intake of omega-3 fatty acids." (PMID 30631281, 2018). "Conversely, STAT6 null mice were resistant to diet induced obesity (DIO) due to enhanced EE, associated with PPARA driven FA oxidative metabolism in the liver and lipolysis and browning (measured by PGC1B and UCP1 expression) in WAT." (PMID 30158466, 2018). "UCP1-KO as well as fatty acid elongase-2 (Elovl2)-KO mice require housing under thermoneutrality to reveal the obesity phenotype." (PMID 29848963, 2018).
Obesity (continued). "Thermogenic adipocytes, including brown and beige adipocytes, ameliorate obesity and metabolic diseases through increases of Ucp1 mediated thermogenesis and energy expenditure." (PMID 30577593, 2018). "The amelioration of obesity in infected mice was accompanied by an intensified UCP1 expression, and increased browning of white adipose tissue, and altered gene expression of key regulators mediating lipid metabolism in gonadal fat." (PMID 29545532, 2018). "Adaptive thermogenesis is dependent on uncoupling protein 1 (UCP1) and produces heat from chemical energy (carbon atoms ingested in the diet), enhancing EE and combating hypothermia and obesity." (PMID 29351550, 2018). "A link between UCP1 and dietary composition of macronutrients has been demonstrated in a number of studies, where rodents fed high protein diets exhibited attenuated obesity development accompanied by increased UCP1 expression and energy expenditure." (PMID 30631281, 2018). "UCP-1 is known to mediate diet-induced adrenergic thermogenesis, where its ablation was found to induce obesity." (PMID 30214412, 2018). "For instance, inactivation of UCP1 due to thermoneutral conditions led to obesity in mice fed both a control diet and high-fat diet, indicating a role of BAT in maintaining a non-obese phenotype." (PMID 28194159, 2017). "These authors also showed that chronic CK2 inhibition by CX-4945-treatment for 40 days protects mice from diet-induced obesity and moderately improves insulin sensitivity by promoting UCP-1 dependent thermogenesis." (PMID 29242563, 2017). "Brown adipose tissue acts antagonistically on dietary obesity by promoting thermogenesis, mainly by uncoupling protein-1 production, which, in turn, accelerates energy metabolism." (PMID 28335584, 2017). "Upregulation of UCP1 by genetic manipulations or pharmacological agents can reduce obesity and improve insulin sensitivity." (PMID 28360931, 2017). "Correspondingly, RA administration to mice reduces obesity by upregulating uncoupling protein-1 (Ucp1) expression both in vivo and in vitro." (PMID 29021914, 2017). "On the other hand, overexpression of UCP1 in white adipose tissue and skeletal muscle of mice, provided protection against diet-induced obesity, increased energy expenditure, and improved glucose homeostasis." (PMID 28194159, 2017). "BAT is a promising therapeutic target for combating obesity and related metabolic disorders due to its inherent capacity for dissipating energy as heat through the action of uncoupling protein 1 (UCP1)." (PMID 28957413, 2017). "Brown adipose tissue (BAT) is a specialized tissue that dissipates energy in the form of heat (nonshivering thermogenesis) by uncoupling FAO from the ATP production via uncoupling protein 1 (UCP1) in mitochondria to protect against obesity." (PMID 27589792, 2016). "The correlation for UCP1 with clinical stage was stronger in “metabolically healthy” patients than in females with “standard” obesity." (PMID 27853670, 2016). "We found that in male Swiss mice with HFD-induced obesity there was preferential induction of thermogenesis-related genes (Ucp-1 and Cidea) in visceral (epididymal) WAT in response to treatment with the TZD-derivative GQ-16." (PMID 27138164, 2016). "Brown adipose tissue (BAT) is considered a potential target for combatting obesity, as it produces heat instead of ATP in cellular respiration due to uncoupling protein-1 (UCP-1) in mitochondria." (PMID 26993316, 2016). "Given the reduced heat production and obesity in mCaROCK1 mice, we analyzed UCP1 expression in inguinal WAT of these mice." (PMID 27411515, 2016).
Obesity (continued). "In fact, BAT hypoxia not only is present in the course of obesity but also is one of the earliest events during cold challenge, likely resulting from the excessive demand of oxygen that is required for UCP1 activity and heat generation." (PMID 26572826, 2016). "We found low levels of UCP1 mRNA in BAT of Mc4rK314X/K314X rats, which also implicated low EE as a potential contributor to obesity in these rats." (PMID 27886210, 2016). "Deletion of UCP1 induces obesity and upregulation of UCP1 increases thermogenesis and energy expenditure in mice." (PMID 27558934, 2016). "Conversely, β1-AR transgenic mice are resistant to diet-induced obesity and display a high abundance of adipocytes expressing Ucp1 in WAT36." (PMID 27941950, 2016). "Another study using the same approach showed that apolipoprotein-2 (Ap2) driven adipose tissue specific overexpression of Ucp1 made mice resistant to obesity induced by a HFD, presumably due to ectopic synthesis of Ucp1 in WAT." (PMID 28105413, 2016). "Genetic inhibition of Tph1 protects or reverses the development of F diet induced obesity and dysglycemia via activation of UCP1-mediated thermogenesis in brown adipose tissue." (PMID 26766570, 2016). "The upregulation of UCP1 induces increased energy expenditure, which contributes to the prevention or reduction of obesity." (PMID 26628904, 2015). "Previous studies have suggested that the UCP1 -3826 A > G polymorphism was related to low HDL-cholesterolemia and low HDL-cholesterol levels in some populations with obesity." (PMID 25928572, 2015). "In particular, its potential anti-obesity effect was primarily detected by murine studies, which displayed an induction of uncoupling protein-1 in abdominal white adipose tissue mitochondria, leading to the oxidation of fatty acids and heat production." (PMID 25871295, 2015). "The UCP1 gene is a candidate gene for obesity and type 2 diabetes mellitus because the gene has been found to decrease mitochondrial membrane potential and increase thermogenesis." (PMID 25646961, 2015). "Nonetheless, the effects of ZAG on UCP1 expression and energy expenditure in murine obesity models of obesity are far from clear." (PMID 26068931, 2015). "β3-adrenergic signaling enhances UCP1 expression through β3-adrenergic receptor (β3AR) and thus plays a role in alleviating obesity." (PMID 26628904, 2015). "The overexpression of UCP1 or activation of BAT thermogenesis has been shown to prevent the development of obesity." (PMID 25713540, 2015). "Increasing PGC-1α and UCP1 expressions are considered to be treatment targets of obesity and obesity-related diseases." (PMID 25963634, 2015). "Recent literature suggests that fucoxanthin plays an anti-obesity effect, mainly by stimulating uncoupling protein-1 (UCP-1) expression in white adipose tissue (WAT)." (PMID 25871295, 2015). "Conversely, over-expression of UCP1 or powerful activation of BAT thermogenesis prevents the development of obesity." (PMID 25658324, 2015). "Stimulation of BAT activity and/or recruitment of UCP1-positive cells are therefore relevant targets for the treatment of obesity/type 2 diabetes in humans." (PMID 25688211, 2015). "A SNP near the uncoupling protein 1 gene (UCP1), namely UCP1-3826G/A, is a promising genetic variation linking cold adaptation and resistance to obesity." (PMID 25533680, 2014). "In conclusion, chronic consumption of 52 mg of vitamin A/kg diet seems to be an effective dose in ameliorating obesity possibly through mitochondriogenesis, UCP1-mediated thermogenesis in BAT and apoptosis in eWAT of obese rats." (PMID 25302071, 2014). "Miglitol’s anti-obesity effect was attributed to increased energy expenditure by upregulating UCP1 in BAT (i.e., by thermogenesis) and to enhancement of β3-adrenergic signaling in BAT." (PMID 24669882, 2014). "The upregulation of UCP1 expression indicates increased thermogenesis and energy expenditure, which helps to protect from fat accumulation and obesity." (PMID 24669882, 2014).
Obesity (continued). "Like other models of obesity (ob/ob, db/db mice and fa/fa rats), obese rats of WNIN/Ob strain show impaired BAT thermogenesis, which is associated with low UCP1 levels in BAT." (PMID 25302071, 2014). "The involvement of UCP1 in adrenergically induced thermogenesis demonstrates that UCP1 plays a significant role in the control of energy expenditure; its dysfunction contributes to the development and maintenance of obesity." (PMID 24159189, 2014). "Galanin receptors and SIRT1 are known to reverse obesity-induced downregulation of UCP1 expression in WAT." (PMID 24624222, 2014). "The UCP1 in BAT explain a significant component of whole body energy expenditure: its dysfunction contributes to the development of obesity, and its expression would also be an attractive target for the development of anti-obesity therapies." (PMID 24796298, 2014). "Our results show that miglitol increased energy expenditure, reduced obesity and enhanced β3-adrenergic signaling and upregulation of UCP1 in BAT." (PMID 24669882, 2014). "β3-adrenergic signaling through the β3-adrenergic receptor (β3AR) activates UCP1 and thus has a role in reducing obesity." (PMID 24669882, 2014). "The A allele of the -3826 site, which increased the UCP1 expression levels, was linked with higher BAT activity and reduced risks of obesity." (PMID 25533680, 2014). "Regardless, it appears that certain regulatory processes are impaired in both UCP-1 transcription and translation in obesity." (PMID 24642703, 2014). "The ability of 2-PCPA to increase body temperature in the light cycle was UCP1 independent, and 2-PCPA-treated UCP1-KO mice were similarly resistant to obesity as WT mice." (PMID 24586592, 2014). "Miglitol 1) increased energy expenditure, 2) had an anti-obesity effect in high fat diet-induced obese mice, 3) enhanced β3-adrenergic signaling and 4) upregulated UCP1 in BAT under the condition of a high fat diet." (PMID 24669882, 2014). "These are the reasons why the roles played by UCP1-3826A/G, UCP2-866G/A, UCP2 Ala55Val, UCP2 Ins/Del and UCP3-55C/T polymorphisms in obesity risk and BMI changes have been extensively studied, although the results of these associations are still inconclusive." (PMID 24804925, 2014). "We found evodiamine decreases diet-induced obesity and glucose intolerance in a UCP1-independent manner in mice." (PMID 24391749, 2013). "As UCP1 has been proved to decrease membrane potential, downregulate ROS generation, and increase energy expenditure, so UCP1 gene is regarded as a candidate gene for obesity, DM2, or related traits." (PMID 23841103, 2013). "Brown adipose tissue (BAT) dissipates energy stored in triglycerides as heat via the uncoupling protein UCP-1 and is a promising target to combat hyperlipidemia and obesity." (PMID 24066098, 2013). "Reports vary, however, from the UCP-1 knockout mouse being obese and especially sensitive to diet-induced obesity when housed at thermoneutrality, to their being resistant to diet-induced obesity when housed at 20°C." (PMID 23580228, 2013). "Genes encoding UCP1 (UCP1) and ADRB3 (ADRB3) have been studied to elucidate genetic variations accounting for the susceptibility to obesity." (PMID 24086366, 2013). "UCP1 is a key protein in thermogenesis and regulation of energy expenditure mechanisms which are important in obesity." (PMID 23861682, 2013). "This signifies the acceleration of energy consumption by the expression of UCP-1 is effective to the prevention and suppression of obesity." (PMID 23043591, 2012). "Considering DP acts as a causative factor of obesity in TKM, and UCP-1 is regulator of obesity, DP and UCP-1 seem to be highly associated each other." (PMID 23043591, 2012). "Rodents resistant to the diet-induced obesity increase BAT thermogenesis via increased UCP-1 activity to avoid weight gain." (PMID 23118773, 2012).
Obesity (continued). "Alternatively, under-nourished mice with suppressed wBAT could be less susceptible to diet-induced obesity because they would be required to use alternative thermogenic mechanisms that are calorically more costly to regulate body temperature, as we have postulated for UCP1-deficient mice." (PMID 22383960, 2012). "UCP1 expression is known to be a significant component of whole body energy expenditure, and its dysfunction contributes to the development of obesity." (PMID 22611357, 2012). "In other animal models of obesity, anti-inflammatory approaches also produced beneficial changes in the expression of UCP1 in BAT." (PMID 22279596, 2012). "The recent discovery of BAT in adult humans has excited interest in combating obesity by stimulating the expression and activity of UCP1 in brown adipocytes in order to increase energy expenditure." (PMID 23293654, 2012). "Uncoupling protein 1 plays an important role in BAT thermogenesis, and mouse studies have shown a link between UCP1 and obesity." (PMID 22980388, 2012). "For obesity, perhaps the most striking result is Ucp1 KO mouse, which when compared to WT controls is lean at 20°C but becomes obese at 30°C." (PMID 23140644, 2012). "Considered as a breakthrough discovery for an ideal therapy for obesity, the regulation of UCP1 expression in tissues other than BAT by food constituents would also be important." (PMID 22611357, 2012). "In our study we investigated the effect of UCP-1 gene SNPs on obesity and obesity related phenotypes among Brazilian people." (PMID 23134754, 2012). "Variants of the SIRT1, SIRT2, SIRT6, UCP1, UCP2, and UCP3 genes have been related to diabetes, obesity, serum high-density lipoprotein cholesterol (HDL), and inflammation." (PMID 22087257, 2011). "Conversely, inhibition of diet-induced expression of Ucp1 in iWAT in Sv129 mice by administration of a general cyclooxygenase inhibitor accentuates obesity-development." (PMID 21738749, 2011). "The amount of BAT and the expression of UCP1 correlate with increased basal metabolic rate and protection from obesity in both mice and humans." (PMID 21193034, 2011). "Consistent with this notion, mouse strains with high content of brown adipocytes in WAT are highly resistant to the development of diet-induced obesity and ectopic overexpression of UCP1 in WAT protects mice against obesity." (PMID 22087241, 2011). "In mouse models, over-expression of UCP1 results in obesity resistance while ablation of UCP1 induces obesity." (PMID 20885954, 2010). "Inhibition of COX activity attenuated diet-induced UCP1 expression and increased energy efficiency and adipose tissue mass in obesity-resistant mice kept at thermoneutrality." (PMID 20613988, 2010). "We suggest that whereas UCP1 in iWAT plays an important role in protection against obesity, UCP1 in iBAT is essential for temperature adaptation." (PMID 20613988, 2010). "Less clear is the roleof UCP1 in human obesity, taking into account the residual amountsof brown adipocytes in adult humans." (PMID 17389766, 2007). "Mice lacking UCP1 exhibit impaired thermogenesis and increased susceptibility to diet-induced obesity." (PMID 41535542, 2026). "Therefore, the whitening of BAT, as indicated by adipocyte hypertrophy, lipid droplet accumulation, uncoupling protein 1 (UCP-1) suppression, and mitochondrial dysfunction, initiates and accelerates obesity progression." (PMID 40520025, 2025). "Therefore, brown adipocytes play a pivotal role in thermogenesis and energy expenditure, and factors regulating UCP1 expression are attractive targets for obesity research." (PMID 40220069, 2025). "The depot-specific UCP1 induction in iSAT correlated with reduced adipocyte size, supporting a role for enhanced thermogenesis in the combinatorial therapy’s anti-obesity effects." (PMID 41471299, 2025).